MAPT (microtubule associated protein tau)
Diseases named in the same sentence as MAPT in open-access papers (continued):
Sharing a sentence is not in itself a finding about the gene and the disease.
Blindness (1 paper, 2011). Blindness is the condition of lacking visual perception defined as a profound reduction in visual perception. "Given the relationship between MAPT variation and altered mitochondrial respiratory chain function, we hypothesised that MAPT variation could contribute to the risk of blindness in LHON mtDNA mutation carriers." (PMID 21397051, 2011). "Our findings suggest that genetic variation in MAPT is unlikely to make a major contribution to the risk of blindness among LHON mutation carriers." (PMID 21397051, 2011).
bone sarcoma (1 paper, 2025). A sarcoma that arises from the bone. "To better understand this aspect, we explored the MAPT expression in each different bone sarcoma, and observed that EwS cell lines presented a significantly higher MAPT expression than osteosarcoma and chondrosarcoma cell lines." (PMID 40319030, 2025).
cervical cancer (1 paper, 2025). A primary or metastatic malignant neoplasm involving the cervix. "Eventually, we obtained a seven-mRNA–lncRNA gene cluster (four mRNAs: ART3, HRG, MAPT, and SYTL5; three lncRNAs: AC011239.1, AC125616.1, and RUVBL1.AS1) that was mostly relevant to LNM of cervical cancer." (PMID 40444278, 2025). "Among these transcripts, AC125616.1, HRG, MAPT, RUVBL1.AS1, and SYTL5 were found to be upregulated, while AC011239.1 and ART3 were downregulated in cervical cancer patients with LNM compared to those without it." (PMID 40444278, 2025).
colon cancer (1 paper, 2016). "The significance of the downregulation of CDX1, FABP1, and MAPT in CTCs is unknown, although associations between the losses of these genes and the development and progression of colon cancer have been described." (PMID 27340863, 2016).
Cri-du-chat syndrome (1 paper, 2023). Monosomy 5p, also known as Cri du chat syndrome, is a rare autosomal deletion syndrome characterized by a mewing cry (cri du chat) in infancy, multiple congenital anomalies, intellectual disability, microcephaly, and facial dysmorphism. "Among these, there are a number of biomedically relevant genes, such as PAK2 affected by 3q29 microdeletion, CTNND2 affected in Cri-du-Chat syndrome, or MAPT affected by 17q21.31 microdeletion (inset)." (PMID 37164484, 2023).
dementia-parkinsonism syndrome (1 paper, 2024). "Overexpression or mutation of neurofilament chain proteins, dynein, peripherin, and microtubule-associated protein tau MAPT (reported in ALS-dementia-parkinsonism syndrome) have been found to induce neurofilament aggregation in ALS." (PMID 37622689, 2024).
familial disease (1 paper, 2014). "In addition to these sporadic diseases, FTD and Parkinsonism linked to chromosome 17 (FTDP-17t) is caused by mutations in MAPT—this genetic form representing the cornerstone piece of evidence for the involvement of tau in non-familial disease." (PMID 25191265, 2014).
Glucose intolerance (1 paper, 2020). Glucose intolerance (GI) can be defined as dysglycemia that comprises both prediabetes and diabetes. "Interestingly, data from genome-wide association studies have shown that the MAPT H1 haplotype is associated with increased glucose intolerance in humans." (PMID 32728795, 2020).
head and neck cancer (1 paper, 2019). A primary or metastatic malignant neoplasm affecting the head and neck. "By contrast, we found an inverse correlation between the expression of Tau/MAPT and the survival of colon and head and neck cancer." (PMID 31551755, 2019).
Hepatic fibrosis (1 paper, 2021). The presence of excessive fibrous connective tissue in the liver. "By mapping the candidate targets to the 66 known genes associated with hepatic fibrosis obtained from OMIM and DrugBank, 10 co-targets were found, including HSP90AA1, PPARG, MAPT, HSP90AB1, STAT1, and PPARA." (PMID 33510287, 2021).
HIV-1 infection (1 paper, 2025). The type species of lentivirus and the etiologic agent of acquired immunodeficiency syndrome (AIDS). "Notably, the top neuronal upstream regulator genes activated by HIV-1 infection in the AD context included APP, presenilin-1, microtubule-associated protein tau (MAPT), and mammalian target of rapamycin (mTOR)." (PMID 40313365, 2025).
hypothyroidism (1 paper, 2024). Abnormally low levels of thyroid hormone. "We found that the 6p22.1 locus and genes, including ZKSCAN4 and MAPT, may play important roles in hypothyroidism and psychiatric disorders." (PMID 38904036, 2024).
infiltrating ductal carcinoma (1 paper, 2024). "Notably, the expression of PINK1.AS, OIP5.AS1, HID.AS1, and MAPT.AS1 was statistically higher in the infiltrating ductal carcinoma subtype." (PMID 38326441, 2024).
Insulin resistance (1 paper, 2019). Increased resistance towards insulin, that is, diminished effectiveness of insulin in reducing blood glucose levels. "J 2 (JAG2), NOTCH3, CDKN1A, HES1, and MAPT are novel biomarkers for the development of insulin resistance." (PMID 30678306, 2019).
insulinomas (1 paper, 2016). "After packaging the expression plasmid into a lentiviral particle, the Rin-5F insulinoma cell line was transduced and subsequently selected for MAPT gene overexpressing cells using puromycin." (PMID 26824039, 2016). "We found upregulation of MAPT protein expression in human insulinomas when compared to human pancreatic islets of Langerhans and an imbalance between MAPT isoforms in insulinomas tissue." (PMID 26824039, 2016). "At first, we evaluated the MAPT expression profile in the human islets of Langerhans from healthy organ donors and from human insulinomas." (PMID 26824039, 2016). "To follow this, we transduced an insulinoma cell line with the 3-repeat domain MAPT, namely, MAPT3 (381aa) isoform, to test its effect on insulin secretion." (PMID 26824039, 2016). "We have previously shown that MAPT is present in human islets of Langerhans, human insulinomas, and pancreatic beta-cell line models, with biophysical similarities to the pathological MAPT in the brain." (PMID 26824039, 2016). "Motivated by these findings, one part of the present study aimed to evaluate MAPT expression levels in human pancreatic islets and human insulinomas." (PMID 26824039, 2016). "To further investigate the role of MAPT in insulin trafficking, we aimed to knock down endogenous Mapt gene in the Rin-5F insulinoma cell line." (PMID 26824039, 2016). "In this study, we demonstrate significant upregulation of MAPT gene and protein expression in human insulinoma tumor tissues when compared to healthy islets of Langerhans." (PMID 26824039, 2016). "We demonstrated MAPT expression in human pancreatic islets of Langerhans and its upregulation in human insulinomas." (PMID 26824039, 2016). "Our finding of 3 times higher MAPT expression in pancreatic insulinomas compared to healthy islets suggests that MAPT might be involved in insulinoma tumor biology." (PMID 26824039, 2016). "We have previously demonstrated MAPT expression in a pancreatic beta-cell line model, human pancreatic islets of Langerhans, and human insulinomas and described biochemical features of pancreatic MAPT that are somewhat similar to the hyperphosphorylated MAPT in AD brains." (PMID 26824039, 2016). "In order to find further proof for this hypothesis, we studied MAPT in a beta-cell derived rodent insulinoma Rin-5F cell line, which represents a model for the evaluation of mechanisms controlling transcription, storage, and secretion of insulin." (PMID 26824039, 2016). "Interestingly, MAPT expression is over 3 times higher in insulinomas when compared to islets, SD ± 0.12 (p < 0.01)." (PMID 26824039, 2016). "Interestingly, the proliferation data could reflect the human clinical data: high MAPT expression level in human insulinomas is going in line with an elevated growth rate of tumor tissue." (PMID 26824039, 2016). "Therefore, we cloned one of the MAPT isoforms; we have chosen the shorter isoform 3RD MAPT (381aa, named also MAPT3) as this occurred in human insulinomas in higher copy number than 4RD." (PMID 26824039, 2016).
ischemic stroke (1 paper, 2021). A stroke disorder caused by obstruction of blood flow to the brain, due to thrombotic (local blood clot formation) or embolic (due to a blood clot or other material traveling from another site) event. "The present study preliminarily investigated the post-translational modifications of MAPT in ischemic stroke." (PMID 33841157, 2021). "The role of MAPT in ischemic stroke has recently attracted wide attention." (PMID 33841157, 2021).
lung diseases (1 paper, 2026). "GWAS analysis revealed risk variants in the MAPT locus in lung diseases." (PMID 41642658, 2026).
mood disorder (1 paper, 2023). A cognitive disorder a disturbance in which the person's mood is hypothesized to be the main underlying feature. "The eQTLs associated with the index level mood disorders are associated with MAPT, KANSL1 and WNT3 transcript levels." (PMID 37336921, 2023).
multiple sclerosis (1 paper, 2022). A progressive autoimmune disorder affecting the central nervous system resulting in demyelination. "In the “inhibition of remyelination in multiple sclerosis: regulation of cytoskeleton proteins”, MAPT—in which Fyn suppression inactivates the guanine nucleotide exchange factor Vav 2 via CDC42—destabilizes the actin microfilaments." (PMID 35804531, 2022).
Nasu-Hakola disease (1 paper, 2020). "In patients diagnosed with AD we found three C9orf72 expansions, nine DVs in MAPT, five in CSF1R, two in GRN, three in PRNP and one each in SQSTM1, TARDBP and VCP, as well as a homozygous TREM2 DV normally associated with Nasu-Hakola disease." (PMID 30279455, 2020).
Neurodegeneration (1 paper, 2013). Progressive loss of neural cells and tissue. "The compact shortest path network included many noteworthy connecting proteins like APP, CREB1, HSP90AA1, MAPT and PTEN which were previously implicated to play critical roles in many neurodegeneration disease pathogenesis and couple of them were indicated to have neuroprotective mechanism." (PMID 24688734, 2013).
Oral ulcer (1 paper, 2022). Erosion of the mucous mebrane of the mouth with local excavation of the surface, resulting from the sloughing of inflammatory necrotic tissue. "Meanwhile, the expression of MAPT gene was lower in the group of patients with oral ulcers, causing a reduction in Tau protein synthesis." (PMID 35958581, 2022). "Among them, the expression of inflammation-related genes such as CCRL2, HLA-C, GSDMB, HLA-DPB1, and MAPT increased in patients with oral ulcers." (PMID 35958581, 2022). "rs17650901 (p=7.54E-12) is located on the gene MAPT, which was differentially expressed in the oral ulcer group." (PMID 35958581, 2022).
periapical abscess (1 paper, 2021). "In the periapical abscess, MAPT and CYP1A2 genes had a prediction of alternative alleles of 0.79 and 0.73 from A>G (rs7521) and C>A (rs762551), respectively." (PMID 34539639, 2021).
pulmonary fibrosis (1 paper, 2018). Chronic progressive interstitial lung disorder characterized by the replacement of the lung tissue by connective tissue, leading to progressive dyspnea, respiratory failure, or right heart failure. "Genome-wide significant loci near MAPT were found to be associated with pulmonary fibrosis." (PMID 29335020, 2018).
renal carcinoma (1 paper, 2017). A carcinoma arising from the epithelium of the renal parenchyma or the renal pelvis. "Thus, further studies are warranted to elucidate the role of MAPT and AUTS2 in renal cancer." (PMID 29215599, 2017).
renal cell carcinoma (1 paper, 2022). "Consistent with renal cell carcinoma, low MAPT expression is associated with a poor overall survival rate, and MAPT RNA interference promotes cancer invasion." (PMID 36188577, 2022).
scrapie (1 paper, 2011). A fatal disease of the nervous system in sheep and goats, characterized by pruritus, debility, and locomotor incoordination. "Remarkable changes of microtubule associated protein tau, regardless of the level or phosphorylating pattern, as well as the relevant kinases, have been also described in the brains of a serial of naturally-occurred human and animal TSEs and scrapie experimental animals." (PMID 21857997, 2011).
serous ovarian carcinoma (1 paper, 2022). "I demonstrate that full-length, truncated, and phosphorylated species of microtubule-associated protein tau are expressed in models of platinum/paclitaxel-resistant high-grade serous ovarian carcinoma." (PMID 36139693, 2022). "The aim of the study was to determine whether targeting microtubule-associated protein tau could reduce cell proliferation and tumor burden in cell culture and mouse models of chemotherapy-resistant high-grade serous ovarian carcinoma." (PMID 36139693, 2022).
sleep disordered breathing (1 paper, 2022). "Of note, measurement of NfL levels can assess neuroaxonal damage related to various etiologies in DM1, such as aberrant splicing of MAPT or other genes regulating synaptic integrity, neurotransmission and neuroinflammation, and sleep disordered breathing." (PMID 35575811, 2022).
squamous cell carcinoma (1 paper, 2021). A carcinoma arising from squamous epithelial cells. "The findings suggest that downregulation of MCM7, MAPT, TGFB2, and THBS1 by MS13 may inhibit cell proliferation and growth as well as metastasis and invasion in squamous cell carcinoma and adenocarcinoma NSCLC cells." (PMID 34299042, 2021).
triple-negative breast carcinoma (1 paper, 2013). An invasive breast carcinoma which is negative for expression of estrogen receptor (ER), progesterone receptor (PR), and human epidermal growth factor receptor 2 (HER2). "Indeed, low ER and MAPT mRNA expression were strongly predictive of sensitivity to ixabepilone in the neo-adjuvant setting, while ixabepilone seems to benefit patients with triple-negative breast cancer." (PMID 23935969, 2013).
uterine cancer (1 paper, 2023). Primary or metastatic malignant neoplasm involving the uterine corpus and/or the cervix. "In uterine cancer cells, high MAPT expression correlated with sensitivity to kinase inhibitors." (PMID 37730697, 2023). "The presence of several correlations between high MAPT expression and response to drugs with various modes of action in bone and uterus-derived cells indicate that MAPT expression may represent a powerful marker to predict response to combination therapies in bone and uterine cancer." (PMID 37730697, 2023).
viral infections (1 paper, 2025). "Lower cognitive performance was associated with CNVs in PSEN1 (exons 1, 9, 12), GRN (exons 1, 6, 12), and MAPT (exons 2, 8), along with viral infections (HSV-1, HSV-2, HAV-2)." (PMID 40725212, 2025). "Genetic analysis identified copy number variations (CNVs) in the APP, PSEN1, PSEN2, MAPT, and GRN genes, while viral infections (HSV-1, HSV-2, CMV, EBV, HIV, SARS-CoV-2, Hepatitis A, B, and C) and vitamin D, B12, and B9 deficiencies were measured." (PMID 40725212, 2025).
neurodegenerative disease (242 papers, 2006 to 2026). A disorder of the central nervous system characterized by gradual and progressive loss of neural tissue and neurologic function. "We demonstrate that RENDER-based delivery of CRISPRoff into induced pluripotent stem cell-derived neurons results in durable repression of the V337M-mutated MAPT gene, thereby reducing protein levels of the neurodegenerative disease associated Tau protein." (PMID 40858609, 2025). "Genome-wide association studies (GWAS) identified several single nucleotide polymorphisms (SNPs) that are in the MAPT locus and are associated with various neurodegenerative diseases." (PMID 40552310, 2025). "In our multivariate GWAS on a large healthy cohort of the UKB, we identified 80 unique independent SNPs with brain stem showing a distinctly high number of specific association signals, which included the MAPT locus implicated in neurodegenerative diseases." (PMID 40512868, 2025). "The microtubule‐associated protein tau (MAPT) gene and its protein product tau are linked to AD and other neurodegenerative diseases." (PMID 40696840, 2025). "Here, we evaluated the SVA67-lncRNA effects on gene expression within the MAPT locus, a region associated with several neurodegenerative diseases in the SH-SY5Y cell line." (PMID 41394315, 2025). "In mammals, tau is predominantly localized to the neuronal axons and promotes microtubule assembly and stability; moreover, mutations in the MAPT locus are highly associated with several neurodegenerative diseases, such as FTD-17." (PMID 40178516, 2025). "Inclusions comprised of microtubule-associated protein tau (tau) are implicated in a group of neurodegenerative diseases, collectively known as tauopathies, that include Alzheimer’s disease (AD)." (PMID 38472475, 2024). "The microtubule-associated protein tau is implicated in neurodegenerative diseases characterized by amyloid formation." (PMID 38313287, 2024). "Mutations in the MAPT gene, encoding for the Tau protein, are thoroughly implicated in various neurodegenerative diseases including AD." (PMID 39346681, 2024). "Microtubule-associated protein Tau (MAPT) is strongly associated with the development of neurodegenerative diseases." (PMID 38790613, 2024). "So far, 60 mutations in the MAPT gene, most of them being missense mutations, have been linked to the onset of neurodegenerative diseases." (PMID 39199184, 2024). "Microtubule-associated protein tau (MAPT) is linked to neurodegenerative diseases and bone metabolism, with dysregulation of MAPT expression potentially causing abnormal bone remodeling." (PMID 39219951, 2024). "More than 30 neurodegenerative diseases are characterized by the pathological aggregation of the microtubule-associated protein tau into insoluble deposits." (PMID 39693350, 2024). "Over 50 mutations in MAPT have been identified to be related to neurodegenerative diseases, most of which are missense mutations." (PMID 38528629, 2024). "We also highlight that SVAs significantly regulate mitochondrial genes as well as genes within the HLA and MAPT loci, previously associated within neurodegenerative diseases." (PMID 38540776, 2024). "Amyloid deposition of the microtubule-associated protein tau is associated with neurodegenerative diseases." (PMID 36959205, 2023). "Mutations in the SNCA, TARDBP and MAPT genes that alter specific amino acids also increase the risk for neurodegenerative disease and are thought to do so by increasing the rate of protein self-association." (PMID 37131250, 2023). "Several prior studies have tried to understand the mechanisms underlying the association of the MAPT H1/H1 haplotype as a major risk factor for several neurodegenerative diseases, including sporadic PD." (PMID 36906636, 2023).